CXCL13 (C-X-C motif chemokine ligand 13)
Diseases named in the same sentence as CXCL13 in open-access papers (continued):
Sharing a sentence is not in itself a finding about the gene and the disease.
immune dysfunction (8 papers, 2016 to 2025). "It has been reported that CXCL13 plays a vital role in many immune diseases through the recruitment of different T-cell subtypes and is a promising therapeutic target in immune diseases." (PMID 37045944, 2023). "The evidence of CD4+CXCL13+ T cells shaping TME composition may represent a LR-CHL–specific mechanism of immune dysfunction, suggesting that therapeutic targeting of these cells might reverse their immunosuppressive effects." (PMID 34615710, 2021). "In summary, serum levels of both CXCL13 and BAFF in NMO patients remained higher during remission, which shows that humoral immune dysfunction persisted during NMO remission." (PMID 28413701, 2017). "CSF CXCL13, CXCL10, IL-6 and IFN-α are elevated in a number of infectious and immune disorders." (PMID 27575749, 2016).
inflammation (7 papers, 2008 to 2025). Aberrant reaction of the microcirculation characterized by movement of fluid and leukocytes from the blood into extravascular tissues. "The best discriminative criterion among investigated chemo/cytokines for differentiating CNS inflammation was the CXCL13 level, with an optimal threshold of 10.9 pg/mL; compared with WBC counts, the corresponding specificity was similar (97%), and the sensitivity was higher (72%)." (PMID 31356620, 2019). "Collectively, these results suggest that CXCL13 produced by Tph cells plays a significant role in the development of iMCD-like systemic inflammation in iMCD-NOS NSG mice, providing a rationale for CXCL13-targeting therapeutic applications in the treatment of iMCD-NOS." (PMID 37907518, 2023). "Elevated CSF CXCL13 levels have been described in HIV patients with clinical signs of CNS inflammation but not in asymptomatic HIV patients." (PMID 23294475, 2013). "Further, this accumulation of B cells correlated with acute brain inflammation measured by MRI and with inflammatory CSF parameters such as the number of CSF leukocytes, intrathecal IgM and IgG synthesis and intrathecal detection of MMP-9 and CxCL-13." (PMID 18596942, 2008).
bacterial infections (6 papers, 2017 to 2025). "However, CXCL13 is also increased in NMO and other neuroinflammatory diseases, and patients with viral/bacterial infections show extremely high CXCL13 levels, therefore, due to low specificity, this chemokine is not suitable as a diagnostic biomarker." (PMID 36143216, 2022). "Nevertheless, we observed that in CVID patients where CRP levels fluctuated between normal and high – likely due to transient viral or bacterial infection - CXCL13 levels did not change significantly, remaining either in the “normal” or “elevated” category." (PMID 41288852, 2025).
renal disease (5 papers, 2021 to 2025). "Tph cells can secrete interleukin-21 (IL-21), interferon (IFN) and C-X-C motif chemokine ligand 13 (CXCL13) to moderate renal disease." (PMID 39390361, 2024). "CXCL13 promoted the proliferation of human renal MCs, and CXCL10 overexpression correlated with clinical LN and showed utility as a new marker to assess renal disease activity in Chinese patients with pediatric SLE." (PMID 38762508, 2024).
brain disease (3 papers, 2013 to 2021). "When assessed during the complete follow-up, both neopterin and CXCL13 were able to indicate the recurrence of brain disease, as their concentration significantly increased in association with relapse." (PMID 23469311, 2013). "ICV administration of anti-CXCL13, which restricted the treatment to the CNS, allowed us to uniquely determine that the observed attenuation of the behavioral manifestations was due to changes in the brain disease progression and not simply secondary to any undetected changes in systemic disease." (PMID 34868008, 2021).
central nervous system disorder (3 papers, 2016 to 2023). A disease involving the central nervous system. "Several studies have demonstrated a strong association between CXCL13 and specific neuroinflammatory diseases when compared to non-inflammatory central nervous system disorders or asymptomatic HIV infection." (PMID 32331231, 2020).
vasculopathy (3 papers, 2020 to 2022). "We report on a patient presenting with basal leptomeningoencephalitis associated with vasculopathy where the chemokine CXCL13 in cerebrospinal fluid played an important diagnostic role." (PMID 35034645, 2022). "Of note, the various CXC chemokines, such as CXCL4 (ELR-), CXCL5 (ELR+), CXCL6 (ELR+), CXCL12 (ELR−), CXCL13 (ELR−), and CXCL14 (ELR−), are thought to be associated with the development of SSc vasculopathy." (PMID 34774095, 2021). "For example, we identified a subnetwork involving endothelial IL33 ↔ macrophage CXCL13 ↔ fibroblast CDKN1A; each component within this subnetwork is associated with vasculopathy, and here we suggest that they interact during metabolic pathology in the aorta." (PMID 34692110, 2020).
connective tissue diseases (2 papers, 2017 to 2022). "For instance, serum concentrations of CXCL13 were increased in patients with idiopathic PAH, connective tissue diseases-associated PAH and chronic thromboembolic PH with weak correlations with hemodynamic parameters in this latter subgroup." (PMID 35967377, 2022).
colon polyps (1 paper, 2022). "The colon polyps demonstrated decreased expressions in CCL5, CCL18, CCL19, CCL21, CXCL12, CXCL14 and CXCL13 genes in this research." (PMID 35486660, 2022).
gynecologic tumors (1 paper, 2024). "Herein, the detailed mechanism of CXCL13 in pan-gynecological tumors deserves further elucidation." (PMID 38459390, 2024).
heart disease (1 paper, 2022). "Interestingly, TgGRK5 cardiomyocytes also showed dysregulated expression of several immune-related genes, including Cxcl11, Cxcl13, and Il-15, that have been previously associated to leukocyte migration and to cardiac dysfunction and remodeling during heart disease." (PMID 33560342, 2022).
hematological malignancies (1 paper, 2022). "CXCL13 was postulated to impact the proliferation, dissemination, and microenvironment interactions of several tumors, including solid cancers as well as hematological malignancies." (PMID 36217194, 2022).
peripheral neuropathy (1 paper, 2019). A disorder affecting the peripheral nervous system. "We next examined serum CXCL13 levels in peripheral neuropathy patients." (PMID 31712675, 2019).
skin disorder (1 paper, 2025). Any deviation from the normal structure or function of the skin or subcutaneous tissue that is manifested by a characteristic set of symptoms and signs. "Public single cell RNA-sequencing atlas of skin disorders and multiplex immunofluorescence were used to explore CXCL13-producing cells." (PMID 40352278, 2025).
CXCL13 also shares sentences with these, for which no sentence is quoted: multiple myeloma (5 papers); esophageal squamous cell carcinoma (4); bacterial meningitis (3); cerebral artery (3); Hodgkins lymphoma (3); lymph node metastasis (3); Lymphadenopathy (3); pseudoexfoliation glaucoma (3); arterial hypertension (2); cataract (2); cerebrovascular disease (2); Crohn disease (2); cutaneous vasculitis (2); encephalomyelitis (2); follicular lymphoma (2); glomerulonephritis (2); Graves disease (2); juvenile idiopathic arthritis (2); lichen planus (2); lung disorder (2); lung squamous cell carcinoma (2); metastatic melanoma (2); mycosis fungoides (2); myelitis (2); Ovarian Tumors (2); pancreatic adenocarcinoma (2); penile cancer (2); prostatic intraepithelial neoplasia (2); Sézary syndrome (2); small cell lung carcinoma (2).
A further 106 diseases each share a sentence with CXCL13 in 2 papers or fewer.